INS (insulin)
Diseases named in the same sentence as INS in open-access papers (continued):
Sharing a sentence is not in itself a finding about the gene and the disease.
Arrhythmia (75 papers, 2009 to 2025). Any cardiac rhythm other than the normal sinus rhythm. "Beyond risk prediction, increasing evidence links Cav-3/caveolae to HF-relevant pathophysiology, including arrhythmia susceptibility and insulin-signaling defects in ischemic or metabolic heart disease—both potential treatment targets." (PMID 41143172, 2025). "Type-1 diabetic mice have altered ion channel kinetics in ventricular and atrial myocytes, that increase the risk of arrhythmia and can be reversed with insulin therapy." (PMID 36050321, 2022). "Plasmatic lipid profile, insulin, cytokines, and arrhythmia susceptibility were determined at the end of the experimental period." (PMID 34202017, 2021). "Amongst patients on insulin, who have more labile glucose control, the spontaneous glycemic fluctuations can induce the occurrence of arrhythmia." (PMID 34545599, 2021). "Caffeine is known to reduce insulin sensitivity in the short term and have adverse effects such as arrhythmias, pregnancy complications, and drug interactions from clinical trials." (PMID 30591664, 2018). "Despite the beneficial effects of metformin and vildagliptin as a single therapy in the present study, we found that only vildagliptin and metformin giving as combined therapy reduced fatal arrhythmias as well as delayed time to the first VT/VF onset during I/R in this obses-insulin resistant rats." (PMID 25036861, 2014). "This beneficial effect of insulin may be related to the amelioration of I/R-induced arrhythmias and cardiac contractile function." (PMID 19706162, 2009). "Moreover, those type 2 diabetics who are partially or fully dependent on insulin are more likely to have severe disease and may be at higher risks of arrhythmias." (PMID 34545599, 2021). "For example, preoperative lung disease and arrhythmias were more prevalent in non-diabetic patients receiving insulin." (PMID 33118731, 2020).
eating disorder (73 papers, 2010 to 2026). A broad group of psychological disorders with abnormal eating behaviors leading to physiological effects from overeating or insufficient food intake. "Recurrent DKA is also known to be caused by insulin cessation, stress from chronic disease, and eating disorders." (PMID 40546498, 2025). "Several factors contribute to the increased risk of eating disorders, including strict dietary control and the desire to maintain physical appearance, often leading to the deliberate omission of insulin for weight loss." (PMID 39334618, 2024). "Recent studies indicate that women are more susceptible than men to experiencing eating disorders and underdosing on insulin." (PMID 39595717, 2024). "Given that males and females can exhibit differences in feeding behavior, and are differentially susceptible to eating disorders and to anxiety-related illness, the need for future studies to examine roles of insulin in both sexes cannot be overemphasized." (PMID 36979453, 2023). "Patients with T1DM are at risk for disordered eating and eating disorders due to specific patterns and featured management, such as insulin-related weight gain and diet for hypoglycemic prevention." (PMID 37710329, 2023). "Among adults with T1D, breaking a perceived dietary ‘rule’, such as consuming more CHO than believed appropriate, is associated with an increased risk of insulin restriction, which is a hallmark of eating disorders in people with T1D." (PMID 37049506, 2023). "Evident in girls, skipping breakfast and lunch were both associated with worse glycaemic control, while breakfast omission was additionally associated with higher eating disorder psychopathology including insulin omission due to weight concerns." (PMID 31882789, 2019). "In summary, this study has documented gender differences in the associations between HbA1c, eating disorder psychopathology, illness perceptions, coping strategies, and insulin beliefs." (PMID 26682231, 2016). "This study aimed to investigate associations between eating disorder psychopathology and illness perceptions, coping strategies, insulin beliefs, insulin restriction, body mass index, and age in young males and females with T1D." (PMID 26529593, 2015). "Eating disorders in young females with T1DM are associated with insulin omission, severe dietary indiscretion, pervasive noncompliance with medical treatment, and poor glycemic control." (PMID 22672865, 2012). "Having observed an increasing trend of eating disorders in the general population in Taiwan, we aimed to investigate clinical and behavioral correlates of disordered eating and insulin restriction behavior and its association with psychological health in a clinical sample of youths with DM." (PMID 37710329, 2023). "Eating disorders were found to be associated with lower insulin adherence and higher HbA1c." (PMID 35673417, 2022). "Among females, eating disorder psychopathology was significantly associated with body mass index adjusted for age and gender, age, insulin restriction, coping, illness perceptions, and perceptions of insulin concern." (PMID 26529593, 2015). "In previous studies of eating disorders in individuals with T1D, the association has been explained by weight gain with insulin treatment, and subsequent body dissatisfaction combined with a possibility to control body weight by modifying insulin dosages." (PMID 25147950, 2014). "Moreover, younger adults with T1DM may have a higher incidence of eating disorders, which can interfere with insulin management and lead to increased risk of DKA." (PMID 39928633, 2025). "Of note, the later ones represent insulin resistant subjects, while in eating disorders – e.g., anorexia nervosa (AN), both increased and diminished insulin sensitivity can be seen, depending on the muscle mass atrophy and abdominal fat accumulation." (PMID 37545582, 2023).
eating disorder (continued). "Some researchers use the term to describe insulin restriction and/or omission for weight and/or shape control, while others use it to describe eating disorders comorbid with T1DM more broadly." (PMID 37255778, 2023). "The main mistakes in the control and supervision of eating habits and, consequently, eating disorders are inconsistent and irregular insulin treatment." (PMID 37764739, 2023). "Strategies to address insulin omission including psychoeducation should be employed to minimise likelihood of progression to a diagnosable eating disorder." (PMID 32128205, 2020). "Insulin restriction in the current study identified a vulnerable subgroup displaying very high rates of eating disorder behaviours, which is similar to previous studies in male and female adults." (PMID 32128205, 2020). "The inclusion of these new guidelines demonstrates that those with T1DM and an eating disorder, specifically insulin omission, pose a unique problem." (PMID 32967730, 2020). "Factors considered to negatively impact glycaemic control include eating disorders and omission of insulin to affect weight control." (PMID 29631570, 2018). "Taken together, these data suggest that NPY is resistant to the insulin mediated mature IGF-II increase occurring in this eating disorder." (PMID 24386136, 2013). "On the other hand, providing the greatest flexibility, continuous subcutaneous insulin infusion may be beneficial in eating disorders." (PMID 41010976, 2025). "Most of the early studies used 160 IU of insulin to uncover the effects of nasal insulin delivery on blood glucose regulation, eating disorders and weight management, however, more recent studies have focused on the use of insulin with lower doses for memory and cognitive behaviour." (PMID 38441832, 2024). "Molecular studies support our findings in a biological context by suggesting atypical signaling from neuroendocrine factors of insulin, leptin, and ghrelin and corresponding gene expressions modulate perturbed inhibitory and reward systems, encouraging eating disorders." (PMID 32785278, 2020). "Intentional insulin omission and eating disorder is quite prevalent among children with T1DM." (PMID 31963630, 2020). "The messages were primarily used to schedule visits (n=25), ask treatment questions such as about insulin dose (n=24); discuss challenges such as eating disorders and feeling alone (n=9); and provide ongoing support such as feedback on glucose measurements (n=13)." (PMID 29945861, 2018). "Other causative factors for higher mean HbA1c concentration in females could be the higher prevalence of eating disorders and insulin purging, which might be of higher importance regarding growth as compared to a temporary impaired metabolic control." (PMID 29238730, 2017). "We have recently demonstrated that adolescent girls with insulin omission eating disorder have a different pattern of HbA1c levels compared with girls with simple poor glycemic control and on this basis have proposed an algorithm for the identification of insulin omission." (PMID 25275650, 2014). "We have also previously shown that eating disorders are common in people with T1D, but in this instance, they believed that insulin treatment would stop weight loss and that was not considered indicative of an eating disorder but rather the biological fact from patients’ own lived experience." (PMID 41497311, 2025). "Medications such as metformin, insulin and semaglutide may alter food consumption and consideration of this, and potential for non-prescribed use needs to be applied in the care of a person living with a higher body weight and an eating disorder." (PMID 35978344, 2022). "Factors that may affect weight gain in patients with T1DM include the level of glycemic control, intensive insulin treatment, pattern of treatment, pubertal status, the presence of eating disorders and appearance of complications (such as thyroid disease or gastric disease)." (PMID 34176476, 2021).
eating disorder (continued). "In addition, insulin omission is a disordered eating behaviour that can often go unrecognised, this may have contributed to the lower reported rates of other eating disorders such as bulimia nervosa." (PMID 34836442, 2021). "Defined as the deliberate reduction or omission of insulin to influence body weight, IIO lies at the intersection of metabolic management and eating disorder psychopathology." (PMID 42123251, 2026). "Furthermore, there are often high levels of secrecy and shame around disordered eating behaviours and eating disorders including insulin misuse, and individuals may be secretive about their engagement in disordered eating behaviours for fear of stigmatisation or due to low motivation for change." (PMID 37255778, 2023). "Children who were managed by insulin injection (n = 84) were found to score lower on self-esteem general and social and higher on T-scored RCADS separation anxiety and eating disorder survey binge eating." (PMID 36508408, 2022). "Factors affecting weight gain include degree of glycaemic control, gender, intensity and mode of insulin treatment (pump versus MDI), the presence of comorbidities such as coeliac or thyroid disease, drug use and the presence of eating disorders." (PMID 34684518, 2021). "The eating disorder is predicted to increase with six DRGs, which are LEP, IL6, GCG, SERPINE1, TNF, and INS." (PMID 32753925, 2020). "Correlations between eating disorder psychopathology and illness perceptions (BIPQ), coping strategies (ACOPE), insulin beliefs (BMQ), insulin restriction due to weight- and shape concerns, age and zBMI." (PMID 26529593, 2015). "In a social context with a relatively lower prevalence of eating disorders, DE/IR behavior is not uncommon among AYAs with DM using insulin as their primary treatment." (PMID 37710329, 2023). "Therefore, future research could test whether Crz and its interacting signaling pathways (insulin, sNPF, NPF;) would regulate feeding behavior in flies in a sexually dimorphic manner, with the potential to expand our understanding of fundamental mechanisms that might underlie eating disorders." (PMID 34287347, 2021). "Except for insulin misuse, there were no statistical differences between the two clinical groups for any other eating disorder related behaviour and psychopathology." (PMID 24885411, 2014). "APE-13 levels appeared to be independent of insulin or glucose levels while correlating with the severity of eating disorder psychopathology, highlighting the need for further efforts to understand circulating neurohormones and neuropeptides and their impact on metabolic health." (PMID 36235674, 2022). "Indeed, diabulimia, an eating disorder where a participant with T1DM does not inject insulin in order to lose weight, is a serious problem in those affected with significant risk of DKA and mortality." (PMID 34530819, 2021). "Furthermore, although insulin restriction is a common feature of disturbed eating in T1D, attitudes toward insulin have not previously been investigated in relation to eating disorder psychopathology in individuals with T1D." (PMID 26529593, 2015).
hyperinsulinemic hypoglycemia (73 papers, 2009 to 2026). An inherited autosomal recessive syndrome characterized by the disorganized formation of new islets in the pancreas and congenital hyperinsulinism. "Patients with reduced BMI after bariatric surgery are at increased risk of postprandial hyperinsulinemic hypoglycemia, particularly those with high insulin secretion and beta-cell function pre-surgery." (PMID 39555226, 2024). "Mutations in HADH have been linked to hyperinsulinemic hypoglycemia, a condition characterized by abnormalities in insulin secretion and recognized as a fatty acid oxidation deficiency disease." (PMID 38649912, 2024). "Insulin autoimmune syndrome (IAS) is a rare cause of endogenous hyperinsulinemic hypoglycemia triggered by insulin autoantibodies." (PMID 39575003, 2024). "Inappropriately high levels of insulin secretion can cause the potentially fatal condition of persistent hyperinsulinemic hypoglycemia of infancy." (PMID 37013583, 2023). "It comprises a group of diseases characterized by a persistent hyperinsulinemic hypoglycemia, due to mutation in the genes involved in the regulation of insulin secretion." (PMID 36210928, 2022). "CHI is caused by inappropriate insulin secretion, leading to recurrent episodes of hyperinsulinemic hypoglycemia, posing a significant risk for impaired neurodevelopment." (PMID 35897673, 2022). "Congenital hyperinsulinism comprises a group of diseases characterized by a persistent hyperinsulinemic hypoglycemia, due to mutation in the genes involved in the regulation of insulin secretion." (PMID 36210928, 2022). "Inactivating variants are recognized owing to insulin over-secretion, resulting in hyperinsulinemic hypoglycemia in infants." (PMID 35002955, 2021). "In adults, these lesions manifest in endogenous adult hyperinsulinemic hypoglycemia, most often caused by an insulinoma, which is an insulin-producing neuroendocrine tumor arising from pancreatic β-cells." (PMID 32385165, 2020). "Hyperinsulinemic hypoglycemia (HH), caused by dysregulation of insulin secretion from pancreatic β-cells, leads to insulin driven glucose entry into the tissues and inhibits glycolysis, gluconeogenesis, fatty acid release, and ketone body synthesis." (PMID 33365210, 2020). "We report a case of a patient with hyperinsulinemic hypoglycemia possibly caused by insulin antibodies induced by insulin analogs and a novel therapeutic measure for this condition." (PMID 30853027, 2019). "ABCC8 regulated K+ channel, and ABCC8/KIR6.2 channels found in insulin-secreting pancreatic beta cells are the cause of monogenic forms of hyperinsulinemic hypoglycemia and neonatal diabetes." (PMID 31607839, 2019). "Hirata syndrome, also known as insulin autoimmune syndrome (IAS), is a rare disorder characterized by hyperinsulinemic hypoglycemia that occurs independently due to elevated serum levels of insulin autoantibodies (IAA), which is commonly associated with HLA-DR4 (DRB1*0406)." (PMID 41589093, 2026). "We believe this to be the first published case of a therapeutic approach to the treatment of hyperinsulinemic hypoglycemia associated with insulin antibodies that factors in blood pH and the correction of acidosis using sodium bicarbonate, which physicians could consider." (PMID 30853027, 2019). "As insulin/C-peptide molar ratios are often used to discriminate exogenous from endogenous hyperinsulinemic hypoglycemia, this raises the risk that maleficent insulin use may be erroneously diagnosed, with potentially decisive implications for criminal and child custody proceedings." (PMID 30085133, 2018). "With a blood glucose of 2.5 mmol/L, an inadequately high insulin, and a low level of β-hydroxybutyrate, the diagnosis of hyperinsulinemic hypoglycemia was established." (PMID 40705962, 2026). "Upon presentation, Whipple's triad was confirmed, and biochemical testing revealed hyperinsulinemic hypoglycemia (plasma glucose: 27 mg/dL, serum insulin: 45.83 mIU/L, C‐peptide: 7.03 ng/mL)." (PMID 40124204, 2025).